DPYSL2 (dihydropyrimidinase like 2)
Diseases named in the same sentence as DPYSL2 in open-access papers (continued):
Sharing a sentence is not in itself a finding about the gene and the disease.
bladder cancer (continued). "Gain- and loss-of-function assays were performed to explore the role of DPYSL2 in bladder cancer growth and metastasis in vitro and in vivo." (PMID 34295887, 2021). "PKM2 silencing completely abolished DPYSL2-enhanced glucose uptake and lactate production in bladder cancer cells." (PMID 34295887, 2021). "High DPYSL2 expression significantly correlated with decreased overall survival and recurrence-free survival of patients with bladder cancer." (PMID 34295887, 2021). "In this study, we demonstrated that DPYSL2 upregulation correlated with tumor staging and poor prognosis in patients with bladder cancer." (PMID 34295887, 2021). "It was shown that DPYSL2 expression was upregulated in bladder cancer tissue compared with adjacent normal bladder tissue and in more aggressive cancer stages compared with lower stages." (PMID 34295887, 2021). "Knockdown of PKM2 completely blocked DPYSL2-induced enhancement of the malignant behavior, glucose uptake, lactic acid production, and epithelial–mesenchymal transition in bladder cancer cells." (PMID 34295887, 2021). "Comparison of clinical features between bladder cancer patients with low and high# DPYSL2 mRNA levels in the TCGA database." (PMID 34295887, 2021). "Our own sequencing data found that the expression level of COMP/DPYSL2 in bladder cancer cases with response to tislelizumab combined with nab-paclitaxel therapy significantly decreased after treatment; however the expression level of TMPRSS4 increased after treatment in non-responsive cases." (PMID 37965307, 2023). "In this study, we demonstrated that in the TCGA dataset, high DPYSL2 expression in bladder cancer tissue significantly correlated with decreased overall survival and recurrence-free survival, along with increased T stage, N stage, clinical stage, and tumor recurrence and progression in patients." (PMID 34295887, 2021). "We found that DPYSL2 overexpression promoted glucose uptake and lactate production, whereas DPYSL2 silencing inhibited glucose uptake and lactate production in bladder cancer cells." (PMID 34295887, 2021). "We further explored the role of DPYSL2 in bladder cancer progression in vivo." (PMID 34295887, 2021). "Considering that PKM2 promotes EMT in cancer cells, we examined whether DPYSL2 affects EMT in bladder cancer cells." (PMID 34295887, 2021). "Importantly, PKM2 silencing completely blocked DPYSL2-induced EMT marker alterations in bladder cancer cells, suggesting that DPYSL2 promotes EMT through PKM2." (PMID 34295887, 2021). "Indeed, DPYSL2 overexpression promoted glucose uptake and lactate production in bladder cancer cells." (PMID 34295887, 2021). "Next, we sought to investigate whether PKM2 mediates the enhancive role of DPYSL2 in the malignant behavior of bladder cancer cells by silencing PKM2 expression in DPYSL2-overexpressing bladder cancer cells." (PMID 34295887, 2021). "In addition, DPYSL2 expression positively correlated with T stage (P = 0.015), N stage (P = 0.011), recurrence and progression (P = 0.012), as well as clinical stage (P < 0.001) in bladder cancer patients." (PMID 34295887, 2021). "The high expression of ABCB9, SPTBN2, GULP1, IGF1, P4HB, NES and DPYSL2 and the low expression of ANXA6, OAS1, RAD9a, DNASE2B and FANCF would be beneficial to the prognosis of bladder cancer patients." (PMID 37845668, 2023). "DPYSL2 overexpression also significantly attenuated E-cadherin protein expression, while enhancing Vimentin and ZEB1 protein expression in bladder cancer cells." (PMID 34295887, 2021). "In this study, we aimed to investigate the role of DPYSL2 and to identify its interacting partner in EMT and aerobic glycolysis during bladder cancer progression." (PMID 34295887, 2021). "However, the involvement of DPYSL2 in bladder cancer progression remains unknown." (PMID 34295887, 2021). "Next, we further explored the role of DPYSL2/PKM2 in aerobic glycolysis and EMT of bladder cancer cells." (PMID 34295887, 2021).
bladder cancer (continued). "In conclusion, the results suggest that DPYSL2 promotes aerobic glycolysis and EMT in bladder cancer via PKM2, serving as a potential therapeutic target for bladder cancer treatment." (PMID 34295887, 2021). "DPYSL2 overexpression significantly attenuated E-cadherin protein expression while enhancing Vimentin and ZEB1 protein expression in bladder cancer cells." (PMID 34295887, 2021). "Mechanistically, DPYSL2 bound to PKM2 and blocked the formation of highly catalytic PKM2 tetramer, which in turn promotes anaerobic glycolysis and EMT in bladder cancer cells." (PMID 34295887, 2021). "Mechanistically, DPYSL2 bound to PKM2 and induced the conversion of PKM2 tetramers to PKM2 dimers, thus promoting aerobic glycolysis and EMT in bladder cancer cells." (PMID 34295887, 2021). "Our results suggest that DPYSL2 binds to PKM2 and inhibits the formation of tetrameric PKM2, which in turn promotes EMT and aerobic glycolysis in bladder cancer cells." (PMID 34295887, 2021). "IHC staining revealed that bladder cancer tissue had remarkably increased DPYSL2 protein expression compared with normal tissue and that MIBC tissue exhibited considerably higher DPYSL2 protein levels than NMIBC tissue." (PMID 34295887, 2021). "In this study, we, for the first time, demonstrated that bladder cancer tissue had remarkably increased DPYSL2 protein expression compared with adjacent non-cancerous tissue on a tissue microarray." (PMID 34295887, 2021). "In addition, DPYSL2 failed to promote glucose uptake, lactate production, and EMT in bladder cancer cells in the presence of glycolysis inhibitor DCA, suggesting that active glycolysis is required for DPYSL2-induced EMT in bladder cancer." (PMID 34295887, 2021). "Importantly, these effects were completely blocked by PKM2 silencing, suggesting that DPYSL2 promotes aerobic glycolysis and EMT via PKM2 in bladder cancer." (PMID 34295887, 2021). "The expression pattern of DPYSL2 in bladder cancer has not been reported yet." (PMID 34295887, 2021). "qRT-PCR and Western blot analysis consistently showed that the mRNA and protein levels of DPYSL2 were significantly elevated in fresh-frozen bladder cancer tissue samples compared with those in adjacent non-cancerous samples, as well as in MIBC samples compared with those in NMIBC samples." (PMID 34295887, 2021). "We found that DPYSL2 failed to promote glucose uptake, lactate production, and EMT in bladder cancer cells in the presence of DCA, suggesting that active glycolysis is required for DPYSL2-induced EMT in bladder cancer." (PMID 34295887, 2021).
lung adenocarcinoma (5 papers, 2021 to 2025). A carcinoma that arises from the lung and is characterized by the presence of malignant glandular epithelial cells. "Previous work has found that Dpysl2 has a decreased expression in lung adenocarcinoma." (PMID 40429836, 2025). "In contrast, lower DPYSL2 expression has been observed in lung adenocarcinoma (LUAD) tissues." (PMID 40869314, 2025). "TMED2, MOESIN, DPYSL2, and LncRNA MEG3 have been discovered to enhance the occurrence and development of patients with lung adenocarcinoma via several immune-related regulatory mechanisms." (PMID 35354488, 2022).
lung carcinoma (5 papers, 2014 to 2023). "The exploration of the Oncomine database revealed markedly lower DPYSL2 level in lung cancer tissues than normal tissues." (PMID 34517904, 2021). "However, high expression of ADAMTS8, CD36, DPYSL2, PLEKHH2, STX11, and TCF21 tends to lead to better prognosis, which coincides with the difference in expression of these HUB genes in normal samples and lung cancer samples." (PMID 37409245, 2023).
autism (4 papers, 2019 to 2025). Persistent deficits in social interaction and communication and interaction as well as a markedly restricted repertoire of activity and interest as well as repetitive patterns of behavior. "The autism risk genes involved in transcriptional regulation (DEAF1) and the cytoskeleton (DPYSL2) were strongly expressed at the end of the lineage." (PMID 39363111, 2024).
glioma (4 papers, 2010 to 2023). A benign or malignant brain and spinal cord tumor that arises from glial cells (astrocytes, oligodendrocytes, ependymal cells). "For DPYSL2, the “glioma versus reference” samples defined an AUC score of 0.985, indicating that it is a promising biomarker." (PMID 28498803, 2017). "Bioinformatic analysis of genes of interest against TCGA RNA sequencing data proposed TRIM28, VIM, NAP1L1 and DPYSL2 as promising “glioma versus reference” biomarkers, and suggested CRMP1, NAP1L1, NUCL, ACTB and VIM for discrimination between GBM and LGG." (PMID 28498803, 2017). "The analysis of the genes of interest using RNA sequencing data from TCGA suggested the possible use of some of them as biomarkers for glioma class differentiation, with DPYSL2 demonstrated as a glioma-specific biomarker." (PMID 28498803, 2017). "Potential use of DPYSL2 as a “glioma versus reference” tissue biomarker, and the roles of some of the suggested biomarkers for class differentiation have been confirmed with qPCR on a small scale study, but need to be validated with a larger sample number." (PMID 28498803, 2017). "That is the case of genes such as GNB2L1, an anchor protein involved in adhesion and migration of human glioma cells, DPYSL2, a promoter of microtubule assembly and neuronal development, TUBA1A or CFL, which controls cell migration and cell cycle progression." (PMID 20735813, 2010). "Our confirmatory qPCR study showed differential gene expression levels for DPYSL2, VIM and TRIM28 in “glioma versus reference” samples." (PMID 28498803, 2017). "Three genes (TRIM28, DPYSL2 and VIM) were able to successfully distinguish gliomas from reference samples." (PMID 28498803, 2017).
lymph node metastasis (3 papers, 2014 to 2023). "Compared to the samples without lymph node metastasis, ADRB2, DPYSL2, LIMCH1, and PIK3R1 were downregulated in samples with lymph node metastasis." (PMID 38057344, 2023).
brain tumors (2 papers, 2025 to 2026). "To this end, we measured the concentrations of LP-PLA2, DPYSL2, and 8-OHdG in 62 patients with different types of brain tumors who exhibited vitamin D deficiency." (PMID 40869314, 2025). "This study aimed to assess the potential significance of DPYSL2, 8-OHdG, and LP-PLA2 in the oncological diagnosis of patients with brain tumors who have a vitamin D deficiency." (PMID 40869314, 2025). "Reports on the role of DPYSL2 in brain tumors are relatively scarce." (PMID 40869314, 2025). "However, we observed a correlation between serum DPYSL2 levels and tumor size (both primary and secondary brain tumors), but not meningiomas." (PMID 40869314, 2025).
leukemia (2 papers, 2020 to 2023). A malignant (clonal) hematologic disorder, involving hematopoietic stem cells and characterized by the presence of primitive or atypical myeloid or lymphoid cells in the bone marrow and the blood. "As DPYSL2 is one of the targets of HHT in leukemia treatment, we then explore the role of DPYSL2 in AML pathogenesis." (PMID 36621846, 2023). "Our research is the first to reveal that HHT can target DPYSL2 in leukemia treatment." (PMID 36621846, 2023).
small cell lung carcinoma (2 papers, 2013 to 2016). Small cell lung cancer (SCLC) is a highly aggressive malignant neoplasm, accounting for 10-15% of lung cancer cases, characterized byrapid growth, and early metastasis. "Although these genes have not previously been reported as lung development genes, the expression levels of the human homolog of Dpysl2 has been reported to be significantly upregulated in the tumors of small cell lung cancer patients." (PMID 27602285, 2016).
alcohol use disorder (1 paper, 2018). "Polymorphism in the DPYSL2 gene was also reported to be associated with alcohol use disorder." (PMID 29593587, 2018).
bladder tumor (1 paper, 2021). "By analyzing the GSE89 and GSE32548 datasets from the GEO database, we found that DPYSL2 mRNA levels were significantly increased in the bladder tumor tissue samples from patients with MIBC compared with those from patients with NMIBC." (PMID 34295887, 2021).
breast tumor (1 paper, 2017). "Other up-regulated proteins of interest with possible roles in regulating breast tumor cell progression included DPYSL2, FAM129B, IL18, NDRG1, NME1, and SERPINB5." (PMID 28174229, 2017).
diabetic foot ulcer (1 paper, 2025). "Furthermore, findings from foundational experiments provide preliminary support for these bioinformatics results, suggesting that the dysregulation of macrophages in diabetic foot ulcers (DFU) may be linked to alterations in DPYSL2 expression." (PMID 40487403, 2025). "Utilizing enrichment analysis from the DSigDB database, we focused on the core genes associated with diabetic foot ulcers (DFU), specifically SAMHD1 and DPYSL2, to identify potential drug candidates." (PMID 40487403, 2025). "This study employed machine learning techniques to identify four key genes—DPYSL2, CIB2, IFI44, and SAMHD1—that potentially play a significant role in the pathogenesis and progression of diabetic foot ulcer (DFU) disease." (PMID 40487403, 2025). "Quercetin may enhance the healing of diabetic foot ulcers by modulating macrophage activity through the regulation of SAMHD1 and DPYSL2, thereby contributing to the recovery process." (PMID 40487403, 2025).
Graves disease (1 paper, 2016). Graves' disease is an autoimmune disorder that leads to overactivity of the thyroid gland (hyperthyroidism).It is caused by an abnormal immune system response that causes the thyroid gland to produce too much thyroid hormones. "A second locus downstream of DPYSL2 is potentially a novel genetic variant in Graves’ disease that requires further confirmation." (PMID 27863461, 2016).
liver disease (1 paper, 2022). "Finally, several genes in the [NASH]vs[NAFLD + HC] signature (e.g. CHST9, DPYSL2) have not been previously implicated in liver disease and could potentially provide novel biological insights into NASH etiology." (PMID 35173224, 2022).
meningioma (1 paper, 2025). A generally slow growing tumor attached to the dura mater. "The analyses revealed a statistically significant moderate positive correlation between sex and Lp-PLA2 concentration (R = 0.46; p = 0.04) in patients with brain metastases and a strong negative correlation between DPYSL2 and sex (R = −0.85; p = 0.008) in patients with meningioma." (PMID 40869314, 2025). "A statistically significant moderate positive correlation was found between sex and Lp-PLA2 concentration in the group of patients with brain metastases, while a strong negative correlation was observed between DPYSL2 levels and sex among patients with meningioma." (PMID 40869314, 2025).
cancer (27 papers, 2010 to 2026). A tumor composed of atypical neoplastic, often pleomorphic cells that invade other tissues. "The regulation of DPYSL2 is closely associated with the mTOR signaling pathway, which is known to promote cell growth and division, regulate macrophage polarization, and is widely implicated in cancer biology." (PMID 40487403, 2025). "Taking into account the chalcones’ capability to act on multiple molecules, we hypothesized that CITs might not only target stathmin but also other microtubule-associated proteins that are deregulated in cancer cells, such as collapsin response mediator protein-2 (CRMP2, also known as DPYSL2)." (PMID 37305581, 2023). "DPYSL2 (dihydropyrimidinase-like 2) and SKI (sphingosine kinase) were found essential in the assembly and stabilization of MT in various cell types and in cancers." (PMID 37466845, 2023). "DPYSL2 is closely related with NSCLC distant metastasis and is a mediator for collapsin response, which can directly promote cancer progression and epidermal-mesenchymal transition (EMT)." (PMID 38057344, 2023). "The present study has also identified genes other than DPYSL2, whose altered expression may reflect RTX anti-cancer properties." (PMID 40137900, 2025). "However, whether DPYSL2 regulates EMT and aerobic glycolysis in cancer remains unexplored." (PMID 34295887, 2021).